DUSP15 (dual specificity phosphatase 15)
Description:
May dephosphorylate MAPK13, ATF2, ERBB3, PDGFRB and SNX6. [Isoform 3]: May play a role in the regulation of oligodendrocyte differentiation. May play a role in the regulation of myelin formation (By similarity). Involved in the regulation of Erk1/2 phosphorylation in Schwann cells; the signaling may be linked to the regulation of myelination (By similarity).
Synonyms: C20orf57; VHY; bA243J16.6; FLJ20645; bA243J16.5
Tractability: Antibody: its Gene Ontology location is reachable by antibodies, with high confidence; UniProt places it where antibodies can reach, with medium confidence; the Human Protein Atlas places it where antibodies can reach. PROTAC: a small molecule that binds it is known.
Target class: Phosphatase; Serine/threonine/tyrosine protein phosphatase; Enzyme; Protein Phosphatase
Gene: Protein-coding gene on chromosome 20 (31,847,637 to 31,870,664, reverse strand). Ensembl gene ENSG00000149599.
Subcellular location: Cytoplasm; Cell membrane (Isoform 3)
Subcellular location (Human Protein Atlas): Cytosol; Plasma membrane
Gene Ontology:
Molecular function: phosphatase activity; protein binding; protein tyrosine phosphatase activity; protein tyrosine/serine/threonine phosphatase activity; protein serine/threonine phosphatase activity
Biological process: dephosphorylation; positive regulation of ERK1 and ERK2 cascade; signal transduction; negative regulation of transcription by RNA polymerase II; regulation of oligodendrocyte differentiation
Cellular component: plasma membrane; cytoplasm
Genetic constraint (gnomAD): Loss-of-function variants: 23 observed, 21.7 expected, observed/expected ratio (o/e) 1.06, 90% interval 0.76 to 1.5. The synonymous counts are far from expectation, so gnomAD's model fits this gene poorly and the ratio says little. Missense variants: 361 observed, 278.73 expected, observed/expected ratio (o/e) 1.3, 90% interval 1.19 to 1.41. Synonymous variants: 143 observed, 106.93 expected, observed/expected ratio (o/e) 1.34, 90% interval 1.17 to 1.54.
Homologues: Orthologues: macaque DUSP15 (99% identical), dog DUSP15 (94% identical), pig DUSP15 (94% identical), mouse Dusp15 (89% identical), rat Dusp15 (86% identical), guinea pig DUSP15 (84% identical), chimpanzee DUSP15 (67% identical). Paralogues in human: DUSP22 (41% identical), SSH2 (26% identical), SSH3 (26% identical), SSH1 (26% identical), DUSP12 (25% identical), STYXL2 (25% identical), DUSP1 (24% identical), DUSP4 (24% identical), DUSP5 (24% identical), DUSP10 (23% identical), DUSP28 (23% identical), DUSP7 (23% identical), and 19 more.
Diseases named in the same sentence as DUSP15 in open-access papers:
DUSP15 is named in the same sentence as 6 diseases in open-access papers, as found by Europe PMC text mining. Sharing a sentence is not in itself a finding about the gene and the disease. The quoted sentences say what the papers report.
attention deficit-hyperactivity disorder (1 paper, 2023). A disorder characterized by a marked pattern of inattention and/or hyperactivity-impulsivity that is inconsistent with developmental level and clearly interferes with functioning in at least two settings (e.g. at home and at school). "DUSP15 has also been associated with ASD which often co-occurs with attention deficit/hyperactivity disorder (ADHD)." (PMID 36730342, 2023).
osteosarcoma (1 paper, 2025). A usually aggressive malignant bone-forming mesenchymal neoplasm, predominantly affecting adolescents and young adults. "By combining the obtained data, we found that DUSP3 and DUSP15 were differentially expressed in osteosarcoma and associated with patients' prognosis." (PMID 39744427, 2025).
cancer (2 papers, 2020 to 2022). A tumor composed of atypical neoplastic, often pleomorphic cells that invade other tissues. "Of note, in classical carcinomas, there was coamplification and overexpression of the R3HDML, TNNC2, and DUSP15 locus at chromosome band 20q11-13, suggesting functional cooperation between these coamplified genes." (PMID 35953834, 2022).
infection (1 paper, 2023). The state of being infected such as from the introduction of a foreign agent such as serum, vaccine, antigenic substance or organism. "Similar, in the chicken, DUSP1, DUSP5, DUSP7, DUSP10, DUSP15, and DUSP16 were significantly downregulated in response to infection." (PMID 36683094, 2023).
DUSP15 also shares sentences with these, for which no sentence is quoted: autism spectrum disorder (1 paper); breast carcinoma (1).